TNF (tumor necrosis factor)
Diseases named in the same sentence as TNF in open-access papers (continued):
Sharing a sentence is not in itself a finding about the gene and the disease.
cancer (continued). "It is important to note that TNFα is a multifunctional cytokine and is engaged in other cancer-related processes such as migration, invasion and angiogenesis, besides promoting cell survival." (PMID 30760700, 2019). "Cancer cell stemness, invasive capability, and metastasis potentials have been perceived to increase in the presence of inflammatory cytokines, Tumor necrosis factor (TNF)-α, and transcription factor NF-κB." (PMID 30740360, 2019). "Several endogenous and exogenous factors influence mitochondrial ROS production, including mitochondrial membrane potential, hypoxia, and nutrient metabolites but also cancer- and immune-related factors like TNF-α and Toll-like receptors." (PMID 30935064, 2019). "Impressively, the SCNE dramatically depressed key circulating pro-cancer inflammatory cytokines (IFNγ, TNFα, IL-6, IL-1α, and IL-1β) in all of the xenograft and 4NQO-1 mouse models tested." (PMID 31572681, 2019). "An overexpression of TNF-α, the most potent proinflammatory cytokine, can stimulate cancer through activation of NF-κB expression." (PMID 31295906, 2019). "Here the authors identify TNFα signaling as a determinant of viability in BRCA2- inactivated cancer cells." (PMID 30626869, 2019). "Here, we examined the role of cancer cells in self-maintenance and promotion of cellular malignancy through the transport of Pgp and TNF-α molecules by extracellular vesicles (membrane microparticles (MP))." (PMID 31137684, 2019). "TNF-α is also known to modulate proliferation, differentiation, and apoptosis or necrotic cell death in several different cell types including HepG2 cancer cells." (PMID 31482051, 2019). "Elevated levels of TNF-α play a role in the pathogenesis of liver inflammation and cancer pathogenesis and increased plasma levels of sICAM-1 have been suggested to be a predictor of HCC development." (PMID 31836844, 2019). "We have described the use of a potent small molecule inhibitor of RIPK1 named GSK’963 for the improvement of the therapeutic window of an antibody-TNF fusion protein (L19-TNF) in preclinical models of cancer." (PMID 31803362, 2019). "It was shown that anti-TNF blocked osteoclast formation, which was recently confirmed in a separate study Only T-cells from osteolysis patients expressed TNF-α, and also osteoclasts derived from cancer patients expressed TNF-α." (PMID 30941138, 2019). "Utilizing pre-ranked GSEA, we showed that primary tumors with Survivors were associated with anti-cancer signaling such as INF-α/-γ response and TNF-α signaling, compared with all recurrence groups in pre-ranked GSEA." (PMID 31729458, 2019). "In all four cases, TNF-α mRNA was seen in a subset of CK-positive cancer cells in the invasive front, whereas expression in (CK-negative) stromal cells was a rare event." (PMID 30999696, 2019). "It is thought that PEV was absorbed into the body and led to antitumor by activation of immune cells that attack malignant tumor cells such as macrophages, NK cells, and TNF-α." (PMID 31467867, 2019). "In particular, TNF-α expression levels in cancer cachexia patients remained a highly controversial topic." (PMID 31788012, 2019). "TNF-α neutralization resulted in a significant reduced CCL8 expression compared with isotype control-treated CM, confirming a role for TNF-α in CCL8 regulation in macrophages exposed to cancer cell CM." (PMID 30930117, 2019). "In many disease states such as inflammatory disease, infections, and cancer, TNFα acts as a major cytokine." (PMID 30818829, 2019). "On the basis of the results above, we concluded that mechanical stresses produced by boiling histotripsy can induce immunogenic cell death of cancers via TNF-mediated necrosis signalling pathway." (PMID 31227775, 2019). "Both nuclear factor kappa B (NF-κB) and tumor necrosis factor-α (TNF-α) are the key factors involved in cancer-related inflammation." (PMID 31191251, 2019).
cancer (continued). "Non-immune cells, such as keratinocytes, astrocytes, endothelial, and epithelial cells but also cancer cells can also express TNF." (PMID 31555271, 2019). "It has been acknowledged that the inflammation and immune responses triggered by TNF-α lead to the progression of cancer and often predict a worse outcome." (PMID 30600678, 2019). "The results of KEGG analysis revealed that DEGs were mainly involved in cytokine-cytokine receptor interaction, TNF signalling pathway, pathways in cancer, NF-kappa B signalling pathway." (PMID 31407623, 2019). "The only clinical testing of TNF-α and RT involves gene therapy delivering TNF-α gene to cancer cells—TNFeradeTM." (PMID 31179236, 2019). "It has been reported that most cancer cells are resistant to TNF-α-induced cell death via increased expressions of survival proteins through the induction transcriptional activity of NF-κB." (PMID 31540489, 2019). "Many studies have shown that inflammatory factors (including interleukins, TNF-α, NF-κB) and the ROS production-induced inflammation infiltrate the inflammatory microenvironment leading to DNA damages and ultimately initiation of cancer." (PMID 31331376, 2019). "During inflammatory processes (including the cancer microenvironment) TNF is one inflammatory mediator that is produced secreted firstly." (PMID 31239840, 2019). "Since the effects on immune cell infiltration and ECM depletion are intertwined, there are several potential clinical applications for TNFα‐CSG in cancer treatment." (PMID 31709774, 2019). "Since expression of TNF-α mRNA was very restricted compared to miR-21, we evaluated the TNF-α positive cancer cells in the four cases for miR-21 positivity within the same cell." (PMID 30999696, 2019). "In their work, the authors cultured cancer cells in a microfluidic chip and exposed them to pulses of tumor necrosis factor (TNF)." (PMID 31001529, 2019). "Considering the dual role TNF plays in anti-cancer immune responses, this point remains a critical issue that needs to be carefully evaluated." (PMID 31727152, 2019). "Increased circulating levels of TNFα and GM-CSF have been found in inflammatory disorders and multiples cancers." (PMID 31581558, 2019). "TNFα has been cited as being responsible for decreasing insulin sensitivity and contributing to insulin resistance in cancer." (PMID 30764482, 2019). "Previous reports suggested that inflammatory cytokines produced in the cancer microenvironment, such as TNF-α, act as a major promotor and modulator of tumorigenesis through activation of EMT and different signaling pathways, including NF-κΒ." (PMID 30917533, 2019). "TNF has long been considered a key regulator of the inflammatory and immune response to cancer, promoting either death or survival under different circumstances." (PMID 31381571, 2019). "Factors involved in EMT in cancer include TNF, IL-1, and IL-4, which in turn activate several transcription factors that promote EMT." (PMID 31337349, 2019). "TNF-α promotes cancer cell death by inducing apoptosis, necroptosis, and autophagy, depending on the conditions of the cells." (PMID 31766230, 2019). "In various cancer cells, curcumin decreases pro-inflammatory signaling related and then inhibits the activation of TNF-α." (PMID 31331376, 2019). "Approximately, 45 formulations, majority of liposomal NPs containing GM-CSF, anti-TNF-α are approved for clinical use in cancer therapy." (PMID 31661003, 2019). "One of the most attractive pro-apoptotic pathways for the treatment of cancer is through the tumor necrosis factor (TNF)-related apoptosis-inducing ligand (TRAIL)." (PMID 30875934, 2019). "When connecting clinical deficits and genes, we identified five clusters that give insights into the biology of frailty: cancer, glucocorticoid receptor, TNF-α, myostatin, angiotensin converter enzyme, ApoE, interleukine-12 and −18." (PMID 31332237, 2019).
cancer (continued). "It was reported that corilagin suppressed the discharge of tumor necrosis factor-α (TNF-α) from carcinoma cells." (PMID 31546767, 2019). "With its clear anti-cancer activity and apoptosis-inducing capacity, it is surprising that it at the same time inhibits TNF-induced necroptotic cell death at concentrations below 10 μM." (PMID 29434255, 2018). "Of these pathways, some pathways were closely associated with cancer development such as Jak-STAT signaling pathway, TNF signaling pathway, Ras signaling pathway and ErbB signaling pathway." (PMID 30400936, 2018). "Overexpression of the cytokine, TNF-α, the most potent pro-inflammatory cytokine so far discovered, can lead to various chronic diseases, including cancer, via the activation of NF-κB." (PMID 29370858, 2018). "Our most intriguing finding is that when TNBC cells are in contact with macrophages or fibroblasts, there is microenvironment-triggered increase in IL1 or TNFα levels, respectively, which can lead to autocrine positive feedback loops in the cancer cells." (PMID 29777109, 2018). "We conclude that cancer septic animals exhibit an increase in a subset of 2B4+ PD-1lo TNF-secreting CD4+ T cells (i.e. Nodes 1 and 2) relative to previously healthy septic controls." (PMID 29338031, 2018). "How to increase the anti-cancer activity of TNFα at a low-dose condition is the key problem which needs to be solved urgently." (PMID 29506556, 2018). "ASPP2 also induced C−C motif chemokine ligand (CCL) 2, CCL5, and tumor necrosis factor-α secretion by cancer cells, thereby promoting macrophage recruitment." (PMID 30389910, 2018). "Both IFN-γ and TNF-α inhibit cancer growth through several mechanisms, including the enhancement of antitumor immunity, and the inhibition of cancer angiogenesis." (PMID 29316940, 2018). "A previous study has shown that telomerase is bound to the promoters of a subset of NF-κB target genes, including IL6, IL8, and TNF-α and stimulate their expression to sustain inflammation and promote cancer progression." (PMID 29986697, 2018). "Both TNF-α and TRAIL are ligands that can trigger apoptosis in susceptible cancer cells by activating their corresponding cell death receptors." (PMID 30459627, 2018). "The tumor necrosis factor (TNF)-related apoptosis-inducing ligand (TRAIL) kills cancer cells but is minimally cytotoxic to normal cells." (PMID 29513749, 2018). "For the DEGs in the yellow module, the enriched pathway was the tumor necrosis factor signaling pathway, transcriptional disregulation in cancer, HTLV-I infection, platinum drug resistance, IL-17 signaling pathway, and endocrine resistance." (PMID 29443735, 2018). "For example, inflammatory cells were activated by increased TNF-α in a paracrine manner, which tipped balance toward cancer invasion leading to decreased survival in OSCC." (PMID 30563540, 2018). "We examined the expression of CAR in human colon (cancer) cells exposed on TNF-α, a well-known factor to induce inflammation." (PMID 30175139, 2018). "Using a Cre-LoxP-based cell fusion assay we demonstrated that the fusion between human M13SV1-Cre breast epithelial cells and human MDA-MB-435-pFDR1 cancer cells was induced by the pro-inflammatory cytokine tumour necrosis factor-α (TNF-α)." (PMID 29636110, 2018). "TNF-α is a major promoter of inflammation-related cancer development among different cytokines, which regulates the pathological condition of IBD." (PMID 30338039, 2018). "Nutraceuticals also can raise natural killer cells (NK) function and tumor necrosis factor (TNF α) in patients with late-stage cancer." (PMID 30563141, 2018).
cancer (continued). "We noted that JAK2/STAT3, TNF-α, mTOR/p70S6K or mTOR/p/0S6K/4E-BP1, and PI3K/Akt/mTOR signaling pathways associated with melittin in cancers were in accordance with the signaling pathway IDs of hsa04630, hsa04668, hsa04150, and hsa04151." (PMID 29854840, 2018). "We further analyzed the role of TNFα in cancer invasion using two-dimensional (2D) and three-dimensional (3D) invasion assays." (PMID 30018735, 2018). "IL-6 and TNF-α are elevated in cancer patients and are able to activate the hypothalamic-pituitary-adrenal (HPA) axis resulting in short sleep duration and sleep disturbances." (PMID 29568412, 2018). "TNF-α takes a paramount role in proliferation during the development and progression in different kinds of cancer." (PMID 30045697, 2018). "Mounting evidence proved that stromal expression of soluble factors including HGF, WNT16B, and TNF-α in the TME has a significant correlation with cancer resistance to chemotherapy, radiation, and targeted agents." (PMID 30333494, 2018). "These particular subunits contribute to cancer formation and invasiveness as a result of their specific transcriptional activity, inter alia via feed-forward loops as in the case of TNFα or telomerase." (PMID 29673141, 2018). "Inflammation too is a key driver in cancer cachexia possibly through increased expression of pro-inflammatory cytokines like IL-6 and TNF-a and induction of acute phase protein response, a key marker of systemic inflammation." (PMID 30482179, 2018). "TNFα is one of the cytokines more studied in cancer and has been correlated to chronic lymphocytic leukemia, Barret’s adenocarcinoma, prostate cancer, breast cancer, and cervical cancer." (PMID 30583555, 2018). "In cancer research, TNF-α was reported to play a role in the progression of cancer by up-regulating the expression of MMP-9 via the activation of ERK1/2, p38, and JNK intracellular signaling pathways." (PMID 29921577, 2018). "This infiltration occurs in several cancers through TNF-α-induced IL-6 to up-regulate STAT3 signaling." (PMID 30567565, 2018). "In the same way, in the setting of cancer cachexia, IL-6 and TNF-α are considered to be critical drivers of lipolysis and fat depletion, with recent evidence of AT production of these cytokines." (PMID 30094378, 2018). "Our results indicate that cancer cell lines significantly upregulated genes associated with M1 monocytes including PDL1, TNF-α, IL-1β, IL-6, IL-8, CCL3, and prostaglandin-endoperoxidase synthase 2 (PTGS2)." (PMID 29668679, 2018). "The cytokines, interleukin 6, and tumor necrosis factor α are known to induce neutrophilia and are involved in acute inflammatory processes and in the pathogenesis of cancer-related inflammation." (PMID 30470260, 2018). "Among which, the genes involved in module 1 (which had the highest score, score = 3.333) were mainly enriched in TNF signaling pathway (p = 4.59E-03), pathways in cancer (p = 5.42E-03), and osteoclast differentiation (p = 6.97E-03)." (PMID 30497506, 2018). "TNF-α is usually considered to be a powerful anticancer agent because of its ability to induce necrosis of cancers." (PMID 29755407, 2018). "For example, inflammatory cytokines, such as IL-6 and TNF-α, are induced in a cancerous environment and induce cancer progression." (PMID 29415668, 2018). "NF‐κB signalling plays a crucial role in cancer stem cell biology 42, and TNF‐α‐induced NF‐κB activation elevated CD44 expression in SCCHN cells, but TRAF6 knockdown markedly attenuated this process." (PMID 29193723, 2018). "TNF-α is known to activate NF-kβ to protect tumor cells, and its upregulation leads to resistance to apoptosis and induces drug resistance in certain cancers." (PMID 29949857, 2018). "Several pro-inflammatory cytokines and their associated pathways, which are known to promote cancer cell proliferation in many cases, were implicated in typical responders throughout this study, including IL6, CCL20, CXCL8, TNF signaling, and IL-17 signaling." (PMID 29983870, 2018).
cancer (continued). "Overall, our results suggest that only the AA/GG genotype essentially predicted cancer patient survival; patients harboring the AA genotype at TNF-α-308 had a shorter lifespan compared to those harboring the GG genotype, with no obvious heterogeneity." (PMID 30407345, 2018). "NF‐κB subunits predominantly exist in the cytoplasm in the inactive state, and they translocate into the nucleus and bind to target DNA sequences after stimulation by TNF‐α in cancer cells." (PMID 29377600, 2018). "In the up-regulated category, the most significant pathways were pathways in cancer, cytokine–cytokine receptor interactions, adherens junctions, and the TNF signaling pathway." (PMID 29587631, 2018). "The role of TNF-α in promoting several tumorigenic activities, including invasiveness, angiogenesis, and metastasis of many cancers has been recognized." (PMID 29748481, 2018). "Human Cytokine Array analysis showed that cancer patients have a significant increase in saliva expression of pro-inflammatory markers IL-1a, IL-1b, IL-6, IL-8, and TNFα compared to controls." (PMID 30018735, 2018). "This possibility is further supported by the finding of increased TNF secretion by CD4+ T cells in cancer septic as compared to previously healthy septic hosts." (PMID 29338031, 2018). "Otherwise, most enriched pathways for induced genes were pathways in cancer, TNF signaling and TGFB signaling." (PMID 30001402, 2018). "TNF-α is a major inflammatory cytokine with a key role in cancer, and with NF-κB central to its activation in HNSCC." (PMID 29464041, 2018). "Although TNF-α-driven modulation of CD44 expression was already reported in several cancers, this is the first time that a strong link has been found between combined inflammatory cytokines and CD44 expression on HSPCs." (PMID 30116149, 2018). "In particular, telomerase directly bound to the NF-κB RELA subunit, thus regulating NF-κB-dependent gene expression by binding κB sites in the promoter regions of IL-6 and TNF-α, both critical for inflammation and cancer progression." (PMID 29673141, 2018). "These endothelial cells also secrete TNFα which helps stimulate cancer cell secretion of CXCL1/2 resulting in increases in cancer cell survival." (PMID 29881724, 2018). "We recently established a direct link between oral inflammation and cancer invasion by showing that neutrophils increase OSCC invasion through a tumor necrosis factor (TNFα)-dependent mechanism." (PMID 30018735, 2018). "On the other hand, impairment of NO-dependent function in the aorta occurred only in the late phase of metastasis formation, most likely as a consequence of robust, cancer-related systemic inflammation mediated by IL-6, TNFα or other mechanisms." (PMID 29788918, 2018). "Consistently, TNF-α's discovery led to great expectations for its use as a therapeutic target for cancer." (PMID 29725601, 2018). "These genes also participated in ECM-receptor interaction, focal adhesion, PI3K-Akt signaling pathway, pathways in cancer and TNF signaling pathway." (PMID 29740513, 2018). "Modification of the TME during EMT occurs as a result of the activity of cytokines, such as IFN-γ, TGF-β and TNF-α which have been shown to induce EMT during cancer progression." (PMID 29440769, 2018). "Next, we elucidated the role of TNFα-primed cancer cells in metastatic colonization through the IL35-mediated signal." (PMID 30218063, 2018). "Despite the increasing relevance of the biological clock in cancer onset and progression, the role of key immune elements, such as TNF, in mediating clock dysregulation in lymphatic cancers remains elusive." (PMID 30065253, 2018). "If TNFα stabilizes cancer cell PD-L1 to engage with PD-1+ TAMs, the activated macrophages are subsequently inhibited." (PMID 30062558, 2018). "Previous studies have reported that pro-inflammatory cytokines, including IL-1, IL-6, TNF-α, and INF-γ, were associated with depressive symptoms in cancer patients." (PMID 30567507, 2018).